Y_RNA (Y RNA )
Gene: Miscellaneous RNA gene on chromosome 9 (61,642,383 to 61,642,494, forward strand). Ensembl gene ENSG00000238933.
Homologues: Orthologues: chimpanzee Y_RNA (100% identical), macaque Y_RNA (91% identical). Paralogues in human: Y_RNA (100% identical), Y_RNA (99% identical), Y_RNA (98% identical), Y_RNA (97% identical), Y_RNA (95% identical), Y_RNA (88% identical), RNY1P5 (87% identical), Y_RNA (87% identical), Y_RNA (86% identical), Y_RNA (85% identical), Y_RNA (84% identical), RNY1 (83% identical), and 101 more.